ACE (angiotensin I converting enzyme)
Diseases named in the same sentence as ACE in open-access papers (continued):
Sharing a sentence is not in itself a finding about the gene and the disease.
anaphylaxis (31 papers, 2011 to 2025). An acute hypersensitivity reaction that occurs from exposure to an allergen. "In particular, beta-blockers, ACE inhibitors/sartans and NSAIDs were associated with a risk of severe or fatal anaphylaxis [10,11▪,12]." (PMID 40699586, 2025). "Beta-blockers, cox-inhibitors and ACE inhibitors have been reported as possible contributors to the severity of all forms of anaphylaxis, and both Beta-blockers and ACE inhibitors have been associated with mast cell priming." (PMID 26635908, 2015). "However ACE inhibitors and ARBs were also significantly associated with the risk of anaphylaxis during general anaesthesia; the role of these drugs as facilitating factors of severe anaphylaxis has already been discussed by other authors especially as regards ACE inhibitors." (PMID 26101469, 2015). "Patients with serum angiotensin converting enzyme l (ACE) levels in the lower quartile of normal (<37.0 mmol/L) have been reported to have a 9.6 (1.6–57) - fold risk of severe pharyngeal edema when experiencing anaphylaxis from a nut source compared to those in the higher quartile." (PMID 26635908, 2015). "Cardiovascular diseases and drugs needed to manage them (ACE-inhibitors, beta-blockers) are important factors making complex and challenging the treatment of anaphylaxis in older adults." (PMID 40699586, 2025). "When induced by angiotensin-converting enzyme (ACE) inhibitors (ACEIs), the mechanism is bradykinin-mediated, rendering conventional anaphylaxis therapies largely ineffective." (PMID 41466925, 2025). "Angiotensin-converting enzyme (ACE) inhibitor therapy should be withheld 24 hours prior to PLEX to prevent symptoms resembling anaphylaxis (flushing, hypotension, abdominal cramping)." (PMID 35291547, 2022). "On the contrary, allergic reactions to Hymenoptera stings, angiotensin converting enzyme (ACE) inhibitors, male sex, serum tryptase levels above 5 ng/mL and systemic mastocytosis were identified as risk factors of anaphylaxis." (PMID 26101469, 2015). "Recent studies of peanut and tree nut anaphylaxis have confirmed lower serum ACE concentrations, <37 mmol/L were 9.7X more likely to develop pharyngeal oedema." (PMID 23316249, 2012). "Our serum ACE levels appear to reflect the genotype findings, with HC and atopics being similar, but anaphylaxis showing significantly lower levels especially for the AACVS subdivision." (PMID 23316249, 2012). "In our study, we have examined plasma renin, 25 hydroxy vitamin D, serum ACE levels, and ACE genotype in 119 controls, 49 atopics, and 120 subjects with prior IgE mediated anaphylaxis." (PMID 23316249, 2012). "This confirmed serum ACE levels were significantly lower in the anaphylaxis group and AACVS subdivision compared with HC and atopics." (PMID 23316249, 2012). "Rarely, symptoms resembling anaphylaxis, such as flushing, hypotension, abdominal cramping, and other gastrointestinal symptoms, have been reported in patients who had taken an ACE inhibitor within 24 to 30 h of plasmapheresis and were receiving albumin for fluid replacement." (PMID 38138254, 2023). "The use of angiotensin-converting enzyme (ACE) inhibitors may impact a patient’s compensatory physiologic response to anaphylaxis, resulting in more severe reactions, although the evidence is conflicting." (PMID 37484849, 2023). "However, drugs that inhibit angiotensin converting enzyme (ACE inhibitors) can exacerbate the clinical effect of this amount of bradykinin to the point of serious adverse effect including anaphylaxis." (PMID 22654591, 2012). "Serum ACE levels may become useful in anaphylaxis since it reflects genotype." (PMID 23316249, 2012). "The authors proposed an algorithm indicating that in patients with AE, the absence of urticaria or multisystem involvement such as anaphylaxis, ACE inhibitor or NSAID usage, or known allergens along with a family history, should prompt consideration of HAE." (PMID 40237768, 2025).
anaphylaxis (continued). "Contrarily to what already stated for food triggers [11▪,12], beta-blockers and ACE-inhibitors are not involved in more severe or fatal anaphylaxis due to Hymenoptera allergy, and they are not a contraindication to immunotherapy." (PMID 40699586, 2025). "Furthermore, the use of angiotensin-converting enzyme (ACE) inhibitors and angiotensin receptor blockers (ARBs) can impact a patient’s compensatory physiologic response to anaphylaxis, leading to more severe reactions." (PMID 22166113, 2011).
liver disease (31 papers, 2005 to 2025). "ACE expression and Ang II levels were increased in DEN-injured rats, unraveling a role of ACE and Ang II as a mediator and therapeutic candidate target in liver disease progression and hepatocarcinogenesis." (PMID 35801591, 2022). "In this study, we identified captopril, an ACE inhibitor, as a generic compound preventing fibrotic liver disease progression toward HCC development." (PMID 35801591, 2022). "Any previous liver disease, chronic use of ACE inhibitors, or receiving palliative care also showed a trend of inclined mortality." (PMID 34938637, 2021). "Livers of fibrotic BDL rats with portal hypertension expressed significantly more mRNA of ACE, MasR and ACE2." (PMID 26406236, 2015). "Next, we studied the functional effect of ACE inhibition on liver disease and HCC." (PMID 35801591, 2022). "Only two genes, ACE and SERPINA, were investigated from the gastroenterological system, both evaluating the potential impacts of GMs on developing portal hypertension." (PMID 40225935, 2024). "To go deeper in the mechanism of action of ACE inhibition and HCC prevention, we investigated the liver disease signaling pathways affected by ACE inhibition using phospho-kinase array analyses of the HCV cPLS system." (PMID 35801591, 2022). "Probably the surplus on angiotensin II generation by increased ACE and AT1 receptor expression is a trigger for increased fibrosis and portal hypertension in our model." (PMID 32392802, 2020). "The role of AngII and Angiotensin-converting enzyme (ACE) in the pathophysiology of cirrhotic portal hypertension should not be overlooked." (PMID 39958826, 2025). "In addition, earlier studies on the ACE gene were shown to increase the chances of developing portal hypertension, yet they have not been further investigated in recent years." (PMID 40225935, 2024).
Anxiety (30 papers, 2011 to 2026). Intense feelings of nervousness, tension, or panic often arise in response to interpersonal stresses. "The combination of APOE and ACE polymorphic variants in bigenic clusters yielded different anxiety and depression patterns at baseline and after one year of treatment." (PMID 22482072, 2012). "For example, our analyses estimated that ACE inhibitors prevent onset of the CCS code labeled “anxiety and fear related disorders” (to a degree that just missed our strict selection criteria)." (PMID 35689299, 2022). "Chronic cerebral hypoperfusion induces ACE/Ang II/AT1R overexpression in the hippocampus and causes anxiety." (PMID 36761172, 2022). "Moreover, experimental studies suggest that ACE regulates neuron proliferation and differentiation in the mammalian brain and influences cognition, anxiety, and memory." (PMID 41459362, 2025). "In addition, 4 other bioactivities have been reported for this peptide over the past 2 decades in MBPDB: increased satiety, anxiety reducing, anticancer, and ACE inhibitory." (PMID 32680863, 2020). "In our study, relative to SHR, CCH in SHR induced significantly activation of the ACE/Ang II/AT1R axis and exacerbated anxiety-like behavior and memory deficits." (PMID 32184813, 2020).
migraine (30 papers, 2008 to 2025). "Migraine is affected by angiotensin-converting enzymes (ACE), and it is common in people with DD allele connecting higher ACE1 activity to more headache assaults." (PMID 34444450, 2021). "Secondly, it is well known that several vascular genetic risk factors, like the methylenetetrahydrofolate reductase (MTHFR) gene and angiotensin I-converting enzyme (ACE) genes, are significantly associated with migraine." (PMID 23566281, 2013). "ACE deletion polymorphisms are more common in patients with migraine." (PMID 29357368, 2018). "Subsequently, a 2010 meta-analysis, which looked at whether C677T polymorphism in the MTHFR gene and the I/D polymorphism in the ACE gene was associated with migraine, showed that the MTHFR 677TT genotype was correlated with an increased risk of migraine with aura." (PMID 35884747, 2022). "For migraine an Italian (Paterna), an Australian (Lea), and a Japanese (Kowa) study has demonstrated different results regarding whether an association between the ACE polymorphisms and this condition exists." (PMID 18366776, 2008). "In conclusion, this present meta-analysis showed that the ACE-DD variant and ESR1-PvuII showed a significant risk of migraine in the Indian population in contrast to LRP1- rs11172113 which showed a protective role in the respective population." (PMID 37925562, 2023). "Two analyses reported on the influence of single gene variants on the migraine-CVD association and showed a modulatory effect of the MTHFR 677C>T and ACE D/I polymorphisms among women." (PMID 21779381, 2011). "Our opinion is that in order for an association to be clinical valuable at least 75–100% of responders to a migraine-prophylactic drug should have a specific ACE-genotype." (PMID 18366776, 2008). "Two small open studies reported an improvement of the headache in migraine patients using an angiotensin-converting enzyme (ACE) inhibitor." (PMID 18366776, 2008). "The endothelin type A receptor (ETA) gene −231 A/A polymorphism and the Angiotensin I-converting enzyme (ACE) deletion/deletion (DD) polymorphism have been associated with migraine, both with and without aura." (PMID 23566281, 2013). "In addition, with respect to the established association between migraine and CVD, the influence of gene variants has recently been investigated, showing for example a modulatory effect of the MTHFR 677C>T and ACE D/I polymorphisms among women." (PMID 21779381, 2011). "Secondly we wanted to investigate the ACE genotype as a possible risk factor for migraine with (MwA) and without (MoA) aura in a Norwegian population." (PMID 18366776, 2008). "Associations between ACE polymorphism and migraine reported in other studies are not consistent and have been detected in different diagnostic or sex categories." (PMID 18366776, 2008). "We also wanted to examine whether a clinical response to an ACE inhibitor, lisinopril, or an angiotensin II receptor blocker, candesartan, in migraine prophylaxis was related to ACE genotype." (PMID 18366776, 2008). "The main objective of this study was to investigate the angiotensin converting enzyme (ACE) genotype as a possible risk factor for migraine (both with and without aura) compared to controls." (PMID 18366776, 2008). "This hypothesis is further strengthened by a very recent systematic review and meta-analysis on the effect of different classes of antihypertensive medications, including alpha-blockers, ARB, ACE inhibitors, beta-blockers, and calcium channel blockers in migraine prevention." (PMID 38311745, 2024). "Overall, the results of this meta-analysis indicated that the ACE-DD variant and the ESR1-PvuII were associated with an increased risk of migraine in the Indian community, while the LRP1-rs11172113 variant was associated with protection from migraine in this population." (PMID 37925562, 2023).
migraine (continued). "The role of RAAS in migraine and CM is further supported by the efficacy of angiotensin receptor blockers (ARB) and ACE-inhibitors in migraine prophylaxis." (PMID 38311745, 2024). "Two randomized, placebo controlled studies conducted by our research group have evidence for efficacy of an ACE inhibitor (lisinopril) and an ARB (candesartan) in migraine prophylaxis." (PMID 18366776, 2008). "Both society guidelines agree on thefollowing classes for migraine prevention: calcitonin gene-related peptides(CGRP) receptor antagonists or antibodies, OnabotulinumtoxinA (Botox),beta-blockers, Angiotensin-Converting Enzyme (ACE) inhibitors, andanti-epileptics." (PMID 41436113, 2025). "In addition, ACE genotype in our experience did not predict the clinical response to lisinopril or candesartan used as migraine prophylactics." (PMID 18366776, 2008).
neurosarcoidosis (30 papers, 2010 to 2025). A sarcoidosis that involves the nervous system. "Only 33% to 50% patients who had elevated ACE levels had neurosarcoidosis, thus a poor contribution to the diagnosis is associated to high level of false positive rate." (PMID 35974942, 2022). "Serum angiotensin‐converting enzyme (ACE) levels were within the reference range, making neurosarcoidosis unlikely." (PMID 41415515, 2025). "Retrospective testing showed elevated CSF ACE, further supporting the diagnosis of neurosarcoidosis." (PMID 41306810, 2025). "CSF markers that help to differentiate are a high CSF protein, pleocytosis, and serum ACE as these are generally normal in MS but do fit with a diagnosis of neurosarcoidosis, whereas intrathecal oligoclonal IgG is more common in MS." (PMID 41328180, 2025). "Diagnostic investigations, including serum levels of angiotensin-converting enzyme (ACE) and calcium, along with MRI of the brain, are crucial for diagnosing neurosarcoidosis." (PMID 39391405, 2024). "Serum biomarkers such as ACE and soluble interleukin-2 receptor (sIL-2R) can be useful in monitoring disease activity, although their utility in neurosarcoidosis specifically is less well established." (PMID 39398844, 2024). "As a 2016 meta-analysis reported, CSF ACE was increased in less than half of neurosarcoidosis cases, and serum ACE in about a third, with our patient also demonstrating normal values." (PMID 39198811, 2024). "In patients with neurosarcoidosis, the serum ACE level decreased significantly after treatment with corticosteroids or corticosteroids combined with MTX, but the decrease in the ACE level in CSF was not as significant as that of serum ACE." (PMID 37868968, 2023). "Several studies evaluated the role of elevated CSF angiotensin-converting enzyme (ACE) level for diagnosing neurosarcoidosis." (PMID 33505980, 2020). "Following the prediagnosis of neurosarcoidosis, the serum angiotensin converting enzyme (ACE) level was 50 U/L (normal is 8–52 U/L) and the CSF IgG index was 0.2 (normal is 0.2–0.5)." (PMID 25810722, 2015). "The value of serum ACE and lysozyme and CSF ACE are limited for diagnosing neurosarcoidosis: sensitivity of serum ACE is 75% in untreated and 35% in treated patients, sensitivity of lysozyme 46% and sensitivity and specificity of CSF ACE is 67% and 67% respectively." (PMID 41328180, 2025). "Additionally, serum ACE and lysozyme levels were within normal limits, further arguing against neurosarcoidosis." (PMID 40688874, 2025). "A combination of neuroimaging, CSF evidence of central nervous system inflammation, histological confirmation of systemic sarcoidosis, or indirect markers such as FDG-PET, gallium scan, or elevated serum angiotensin-converting enzyme (ACE) supports a diagnosis of neurosarcoidosis." (PMID 41306810, 2025). "Angiotensin converting enzyme (ACE) levels in the CSF were very high (159,000 U/L), which may confirm the diagnosis of neurosarcoidosis." (PMID 38255684, 2023). "For a diagnosis of probable neurosarcoidosis, laboratory support (CSF or MRI) is required as well as evidence of systemic sarcoidosis (histological, Kveim test, and/or two or more indirect indicators: suggestive Gallium scan, chest imaging, or serum ACE)." (PMID 22379457, 2011). "Contrary to common belief, ACE level in CSF has poor sensitivity and specificity for neurosarcoidosis and may not have a significant added diagnostic value." (PMID 39274281, 2024). "While serum biomarkers like angiotensin-converting enzyme (ACE) and imaging studies such as chest X-rays are valuable in diagnosing systemic sarcoidosis, their utility in neurosarcoidosis is limited." (PMID 39398844, 2024). "Negative serum ACE and lysozyme levels also helped exclude alternative inflammatory etiologies, such as neurosarcoidosis." (PMID 40688874, 2025). "CSF also resulted negative for the presence of angiotensin-converting enzyme (ACE) and 14-3-3 protein, ruling out neurosarcoidosis and prion disease, respectively." (PMID 39246926, 2024).
neurosarcoidosis (continued). "With no signs of mediastinal lymphadenopathy in the CT scan of the chest and nonelevated serum ACE and sIL2-R levels, neurosarcoidosis seemed less likely." (PMID 32973648, 2020). "In particular CSF examination, ACE levels and HRTC are needed to exclude the hypothesis of neurosarcoidosis." (PMID 30035121, 2018). "Angiotensin-converting enzyme (ACE) levels are not specific for neurosarcoidosis." (PMID 35974942, 2022). "However, the measurement of soluble interleukin-2 receptor (sIL-2R) in CSF, although nonspecific, has emerged as a potentially useful biomarker for neurosarcoidosis, particularly in the absence of elevated angiotensin-converting enzyme (ACE) or lysozyme levels." (PMID 40959368, 2025). "Although the angiotensin-converting enzyme (ACE) level in CSF has been proposed as a potential biomarker, it is relatively nondiagnostic and of unclear value for neurosarcoidosis." (PMID 39274281, 2024). "Angiotensin-converting enzyme (ACE) activity on serum and CSF was negative excluding neurosarcoidosis." (PMID 33228741, 2020).
uveitis (30 papers, 2012 to 2025). An inflammatory process affecting a part of or the entire uvea. "Serum concentrations of sIL2R and ACE were measured in patients with active uveitis." (PMID 26799486, 2016). "Since in real life some uveitis patients will be taking ACE inhibitors during screening, we did not eliminate them from the calculation." (PMID 26799486, 2016). "The serum ACE activity has not been investigated in HLAB27 positive AS related uveitis." (PMID 26879979, 2016). "The laboratory data indicated blood tests such as ACE levels, rheumatoid factor, anti-CCP level, cytoplasmic-antineutrophil cytoplasmic autoantibody (C-ANCA) level, and ANA status appeared to have a maximum of negative results among patients suffering from uveitis." (PMID 37416043, 2023).